INS (insulin)
Diseases named in the same sentence as INS in open-access papers (continued):
Sharing a sentence is not in itself a finding about the gene and the disease.
tumor (continued). "In the five mice that maintained euglycaemia after alloantigen rechallenge, histological analysis demonstrated insulin positive islets embedded within the tumor and localized preferentially close to the kidney." (PMID 20436918, 2010). "Laboratory data, including measurement of tumor markers, were within the normal ranges, and her insulin and glucagon levels were also within the normal ranges." (PMID 20825631, 2010). "Administration of large doses of insulin restored HSPG synthesis in basement membrane following reduction of HSPG by implantation of Engelbreth-Holm-Swarm (EHS) tumor cells in diabetic mice." (PMID 19695080, 2009). "Fish oil probably not only attenuates the tumour-induced inflammatory response, but also normalises the insulin resistance present in the cachectic state." (PMID 19259092, 2009). "One possible explanation for the significantly delayed tumour growth despite constant blood glucose levels in mice of the KD group is the ability of ketogenic diets to significantly reduce blood insulin levels." (PMID 18447912, 2008). "PTEN is a tumour suppressor involved in cell cycle progression as an inhibitor of insulin (INS) signaling." (PMID 19259416, 2008). "These mice express the simian virus large T antigen under the control of the rat insulin promotor and reproducibly develop tumours of the insulin-producing β cells of the islets of Langerhans." (PMID 17179989, 2007). "The principal bifurcation in the clustering occurred between the group that included the normal specimens and the three tumors with a predominance of insulin expression, on one hand, and the other tumor types on the other." (PMID 15691381, 2005). "Repeated treatment with streptozotocin selected toxin resistant subpopulation of insulin producing tumor RINmS cells, characterized increased level of insulin content and secretion." (PMID 11467414, 2000). "Our recent in vitro study suggests that such an approach can be extended and utilized for the selection of tumor-derived insulin-producing cells for transplantation." (PMID 11467414, 2000). "Tumour development and incidence, 3H-thymidine incorporation and insulin content in tumours, the host's food intake, blood insulin, glucose and cholesterol were determined in non-diabetic and alloxan-diabetic mice." (PMID 2186773, 1990). "The stimulation of tumour growth by insulin was counteracted by the inclusion of 3-hydroxybutyrate in the drinking water without any alteration in the extent of weight loss." (PMID 2736199, 1989). "Animals fed the 80% MCT diet had a significantly reduced tumour weight compared with controls fed a normal laboratory diet, while in animals administered 20 U insulin kg-1 day-1 the tumour weight was 50% greater than in saline infused controls." (PMID 2736199, 1989). "Depletion of both carcass fat and muscle dry weight in animals bearing the MAC16 tumour was reversed in animals administered either insulin or an 80% MCT diet." (PMID 2736199, 1989). "Theophylline significantly increased insulin release from 2 tumours with a small stimulatory effect on the third." (PMID 2825749, 1987). "After 3 days of culture in RPMI-1640, tumour pieces released 11-158 mg insulin kg-1 dry wt during acute 60 min incubations with the concomitant uptake of 2-47 mmol 45Ca kg-1 into the intracellular lanthanum-nondisplaceable pool." (PMID 2825749, 1987). "Plasma glucose and insulin responses to glucose and arginine were suggestive of tumour recurrence by 12 days." (PMID 2877684, 1986). "Surgical resection of the tumour resulted in an immediate fall of plasma insulin, attaining concentrations similar to those of anaesthetised control rats by 10 min." (PMID 2877684, 1986). "Glucose tolerance was impaired 1 day after tumour resection despite the coexistence of raised insulin concentrations." (PMID 2877684, 1986).
tumor (continued). "Adaptive browning, regulated by transcriptional drivers such as PRDM16, PPARγ, and PGC1-α, mitigates metabolic inflammation, enhances insulin sensitivity, and may exert tumor-suppressive effects." (PMID 41848823, 2026). "Such tumors cause hypoglycemia with low insulin/C-peptide; here insulin was markedly elevated; no tumor identified on imaging." (PMID 41589093, 2026). "We explore how GLP-1 RAs may affect tumour biology and treatment tolerance, including their impact on visceral fat, insulin resistance, and systemic inflammation." (PMID 41806363, 2026). "Furthermore, MIENTURNET integrative pathway and network analyses of miRNAs identified 470 target genes, many of which play a role in insulin sensitivity, lipid metabolism, gluconeogenesis, oxidative stress and/or tumor metabolism." (PMID 41987891, 2026). "Insulin and insulin‐like growth factor signalling may directly promote tumour growth and progression through tumour cell‐specific mechanisms, including increased cell division, glucose metabolism, and epithelial‐to‐mesenchymal transition." (PMID 41287203, 2026). "The first theory proposes that environmental factors, such as tobacco, may damage beta cells that produce insulin and promote tumor growth." (PMID 41366957, 2025). "Notably, all three tumour samples contained two transcriptionally distinct insulin-expressing tumour cell populations (INS+ and INS+FOSlow), characterised here for the first time." (PMID 40438247, 2025). "However, HK2 expression is markedly upregulated in a wide range of malignant tumours, reflecting its dual regulation by insulin signalling and oncogenic drivers." (PMID 41586225, 2025). "In Patient 2, most cell populations were present in similar proportions in both the primary tumour and the metastatic lesion, with 69.0% of cells in the metastasis expressing insulin, and an increase in proportion of cells in the INS+ cluster compared to INS+FOSlow." (PMID 40438247, 2025). "LOXO-783 causes significant tumor regressions in several PI3Kα H1047R-mutant ER+ HER2− breast cancer models without causing significant weight loss or any increase in insulin or C-peptide." (PMID 39717717, 2025). "Often overlooked, analyses of endocrine cells can be skewed by what is resected and sampled: the head-versus-tail location, proximity to the tumour/margins, and preanalytical factors (e.g., cautery, ischaemia/time to fixation) all influence the islet morphology and hormone staining for insulin." (PMID 41226286, 2025). "For instance, local angiogenic factors within the ECM, which promote tumor vascularization and alleviate tumor hypoxia, as well as endocrine factors like insulin/insulin-like growth factor and sex hormones (e.g., androgens, estrogens, progesterones), can significantly impact proliferative signaling." (PMID 39626263, 2025). "Its insulin-lowering action may indirectly limit tumor growth given the role of insulin and IGF-1 in PC development and progression." (PMID 40940951, 2025). "It is well documented that insulin facilitates tumor cell proliferation and survival." (PMID 40620232, 2025). "NCT01101438 focuses on breast cancer and specifically tests whether measurements of insulin sensitivity can anticipate the tumor shrinkage seen after pairing metformin with standard chemotherapy." (PMID 41010968, 2025). "Since IGF-I exhibits much stronger mitotic and antiapoptotic activity than insulin, this characteristic may contribute to tumor growth and metastasis, ultimately resulting in both metabolic and mitogenic effects." (PMID 40431387, 2025). "On the other hand, exercise has been shown to influence tumor biology through multiple mechanisms, including improving insulin sensitivity, reducing systemic inflammation, and modulating the tumor microenvironment via effects on immune function, oxidative stress, and epigenetic regulation." (PMID 40629272, 2025).
tumor (continued). "Additionally, removing ImpL2 from Yki tumours led to increased insulin signalling in the fat body, as indicated by a decrease in expression of InR, a gene that is upregulated when insulin signalling is low65." (PMID 40275022, 2025). "However, indirect parameters (low IGF‐I, low insulin/C‐peptide, positive glucagon test) and clinical resolution post‐tumour excision strongly support the diagnosis." (PMID 40697895, 2025). "This then means that, if elevated, MAPK signaling could be contributing a lot to increased cell proliferation and survival, thereby contributing to tumor growth and progression, and this phenomenon can be observed in a few insulin-resistant states." (PMID 40989682, 2025). "Furthermore, high insulin levels boost tumor cell glucose uptake through the upregulation of Glucose Transporter 1 (GLUT1) transport proteins, thereby meeting the energy demands required for their rapid growth." (PMID 41164182, 2025). "By lowering IGF-1 and insulin, IF modulates the inflammatory tumour microenvironment." (PMID 41335382, 2025). "To further elucidate changes in systemic and local metabolism in PyMT-RIDad mice, we conducted a comprehensive evaluation of metabolic parameters, including systemic glucose tolerance, insulin sensitivity, lipid clearance, and triolein uptake, while monitoring tumor development." (PMID 40526430, 2025). "In contrast, exogenous insulin may activate mitogenic pathways and promote tumor cell proliferation and angiogenesis via IGF-1 receptor activation." (PMID 40764810, 2025). "While insulin may encourage cell proliferation and tumor growth, the specific mechanisms involved and the extent of the associated risk are still being investigated and warrant further research in future studies." (PMID 40491970, 2025). "Notably, STX-478 at 100 mg/kg displayed anti-tumor activity similar to 50 mg/kg alpelisib but with minimal effect on insulin-mediated glucose clearance in mouse model." (PMID 39717717, 2025). "There have been suggestions that the growth factor (anabolic) properties of insulin could be tumour‐supportive." (PMID 40035222, 2025). "Crosstalk between insulin and insulin-like growth factor (IGF) signaling and oncogenic pathways such as PI3K/AKT/mTOR provides a mechanistic basis for these associations, highlighting the interplay between metabolism and tumor biology." (PMID 41157306, 2025). "Dysregulation of insulin signaling can activate the PI3K/Akt/mTOR and Ras/Raf/MAPK pathways, which may enhance cell proliferation and increase the risk of neoplasia in the breast." (PMID 41463284, 2025). "PTPRN2_AS1 can adsorb miR-145-5p through the ceRNA mechanism, thereby relieving its inhibition on PTPRN2 and enhancing the activity of the insulin signaling pathway, promoting tumor cell glycolysis, which also crucial in the energy metabolism reprogramming of OSCC." (PMID 41287790, 2025). "By raising SHBG, improving leptin sensitivity, and decreasing excess insulin-mediated signalling, nutritional and therapeutic ketosis may attenuate this endocrine, paracrine and autocrine growth axis and re-sensitise tumour cells to apoptotic initiation." (PMID 41586225, 2025). "Additionally, there is a need to establish if both insulin and amino acid availability are required to synergistically induce muscle protein synthesis in tumour‐bearing mice." (PMID 40931444, 2025). "Given that ghrelin inhibits insulin release, it will be important to determine whether LEAP2 has the opposite effect, potentially enhancing insulin secretion or promoting tumor proliferation." (PMID 41488138, 2025). "Indeed, insulin signaling plays a crucial role in cancer regulation and influences tumorigenesis, tumor progression, and response to treatment." (PMID 39395115, 2025). "This form may arise from cytotoxic lymphocyte-mediated insulin resistance or tumor lysis-induced inflammation." (PMID 41137338, 2025).
tumor (continued). "This may reflect the role of central adiposity, better captured by waist circumference, in elevating insulin, inflammatory cytokines, and growth factors that promote aggressive tumor behaviour." (PMID 40475001, 2025). "In addition, elevated insulin levels frequently lead to increased hydrogen peroxide production, exacerbating oxidative stress and furthering genetic damage in tumor cells." (PMID 40212965, 2025). "These interactions highlight a potential metabolic regulatory mechanism that distinguishes normal tissue from cancerous regions, suggesting that insulin resistance may serve as a key barrier to tumor spread." (PMID 40969325, 2025). "Evidence suggests that a high-fat Western diet may promote the growth of NEN, while a Mediterranean diet may help lower insulin levels and strengthen the immune system, potentially preventing tumor development." (PMID 39395115, 2025). "Insulin may promote tumour development via its mitogenic and anti-apoptotic effects and inducing low-grade chronic inflammation." (PMID 40307439, 2025). "HK2 is abundantly expressed in insulin‐sensitive regions such as cardiac, skeletal muscle, and adipose tissues, and its expression is also markedly elevated in highly oxygen‐consuming tissues, such as tumour tissues." (PMID 40415238, 2025). "Besides the normalization of chromogranin A, insulin, and gastrin concentrations, an objective tumor response occurred in 10% of the cases, SD in 80% of the cases, and PD in 10% of the cases." (PMID 39996718, 2025). "Metformin, for instance, is thought to exert anticancer effects by activating the AMPK pathway, reducing insulin resistance, and inhibiting mTOR signaling, which may suppress tumor growth." (PMID 40364115, 2025). "In these cases, the possible mechanisms responsible for insulin-mediated tumor formation may include enhanced DNA synthesis leading to excessive cell growth, inhibition of apoptosis, and alteration of the sex hormone environment." (PMID 39802656, 2025). "For instance, tumours with high GLP-1R expression or those characterized by dysregulation of insulin/IGF signalling pathways may represent more responsive targets." (PMID 41300804, 2025). "Notably, RLY-2608 at 100 mg/kg displayed anti-tumor activity similar to 50 mg/kg alpelisib but with a nominal effect on insulin and C-peptide levels in the mice models." (PMID 39717717, 2025). "Interestingly, pancreas of PKC-Lfng mice contain morphologically normal acinar cells as well as tumor cells that express insulin, which are rarely seen in PKC-Mist1 and PKC-Sox9 mice." (PMID 39548190, 2025). "It has been hypothesized that myosteatosis could stimulate tumour growth through an insulin resistance‐related pathway where inflammatory adipokines are secreted by adipocytes in the skeletal muscle tissue." (PMID 38263932, 2024). "The FOXO signaling pathway is activated in response to growth factors, insulin, oxidative stress, and hypoxia and is capable of controlling several specific gene expression programs, in particular those suppressing tumor growth through induction of apoptosis genes and cell cycle arrest." (PMID 39652576, 2024). "Furthermore, it has been observed that insulin-resistant tumor tissues exhibit enhanced inflammatory responses and increased secretion of inflammatory factors, such as TNF-α and interleukin-6 (IL-6)." (PMID 38449844, 2024). "Long-term consumption of Keto diet reduces insulin levels, which may reduce insulin–insulin-like growth factor 1 receptor–mediated tumor growth and progression." (PMID 38838145, 2024). "Several physical activity–mediated mechanisms have been proposed to elicit tumor growth-inhibiting effects, including modulation of hormonal/growth factors (e.g., insulin/insulin growth factor, testosterone), release of myokines, improved immune function, and changes in tumor vascularization." (PMID 38079310, 2024).
tumor (continued). "IRS-1, the critical molecule downstream of insulin and insulin-like growth factor 1 receptor, can be ubiquitinated by Cul7 E3 ligase, suggesting that this tumor-suppressing activity may be related to Cul7-mediated degradation of IRS-1." (PMID 39852134, 2024). "In tumor cells, estradiol treatment increases insulin-assisted glucose uptake." (PMID 39329990, 2024). "The daily carbohydrate restriction (20 – 50g/day) inherent to a WFKD leads to a reduction in plasma insulin and glucose levels, thereby increasing reliance on fatty acid oxidation over glucose, which may favorably influence local tumor and systemic metabolism." (PMID 38166036, 2024). "At the last examination, 50% of the tumor cells expressed gastrin and 5% insulin." (PMID 39382626, 2024). "Additionally, the human granulosa-like tumor cell line KGN is subjected to insulin incubation to assess the impact of lncRNA SNHG12 on GC proliferation and apoptosis." (PMID 38566229, 2024). "Additionally, IR was identified as a critical factor, likely due to insulin’s role as a growth factor for colonic cells and its mitogenic effect on tumor cells." (PMID 39409969, 2024). "Tumor growth in obese people may be impacted by chronic hyperglycemia, increasing circulating insulin levels, elevated glucocorticoids, increased inflammation, and other associated processes on systemic glucose metabolism." (PMID 38541801, 2024). "Although modern literature establishes a neoplastic role for insulin, so that the hormone use is related to tumor emergence/growth, the present study is supported by data from the beginning of the 20th century, in which it was demonstrated that insulin showed antineoplastic activity." (PMID 38658239, 2024). "Although βHC-9 cells, which are derived from mouse pancreatic islets, can secrete insulin in response to glucose in a concentration-dependent manner, they originate from the hyperplastic islets of transgenic mice expressing the simian virus 40 tumour antigen." (PMID 38731926, 2024). "We hypothesized that consuming a low GI diet would inhibit tumor growth by decreasing the activation of the insulin/IGF-1 signaling axis compared to a high GI diet." (PMID 38082056, 2024). "Given the role of glucose and insulin in promoting tumor growth, we hypothesized a low GI diet may slow tumor growth." (PMID 38082056, 2024). "Furthermore, we observed that Aqp1 expression had no detrimental effects on native biological activities, such as phagocytosis, immune response, insulin secretion, and tumor cell migration in the analyzed cell lines." (PMID 38649904, 2024). "Relevant to tumor development, adiponectin may exert indirect effects by enhancing cell sensitivity to insulin or through anti-inflammatory actions." (PMID 38255203, 2024). "The production of SCFAs can inhibit the growth of pathogenic microorganisms, improve intestinal microenvironment, regulate host blood sugar and lipid metabolism, promote nutrients, improve insulin sensitivity, inhibit inflammation and tumor cell invasion and metastasis." (PMID 38254574, 2024). "Blocking RAGE in CAFs may reduce tumor growth driven by insulin signals, as evidenced by the cross-talk between RAGE and insulin receptors." (PMID 39830522, 2024). "Targeting pathways linked to 3-methyl-2-oxovalerate, such as branched-chain amino acid metabolism and insulin resistance-related signaling, could offer novel approaches to inhibit tumor growth and progression." (PMID 39736510, 2024). "Inhibition of PTP1B compensates for insulin signaling pathway and enhances anti-tumor immunity." (PMID 37949850, 2023). "Cluster 1 comprises genes important for skeletal muscle (ACTA1) and muscle function (ACTN1) and includes a crucial gene (AKT1) known to regulate insulin signaling, cell survival, and tumor progression, as well as two chaperones: HSPA1A and HSPB1 (heat shock proteins (HSPs))." (PMID 36767649, 2023).